VCAM1 (vascular cell adhesion molecule 1)
Diseases named in the same sentence as VCAM1 in open-access papers (continued):
Sharing a sentence is not in itself a finding about the gene and the disease.
atherosclerosis (continued). "We confirmed that utilization of blocking antibody targeting CD29 specifically prevents arsenic-induced monocytes adhesion to VCAM-1, suggesting the biological importance of this integrin in arsenic-induced atherosclerosis." (PMID 26332580, 2015). "Since VCAM-1-facilitated recruitment of leukocytes from the circulation is an initial step in many inflammatory disorders, including atherosclerosis." (PMID 26042828, 2015). "VCAM-1 expression is uniquely upregulated upon atherosclerotic stimuli, and exacerbation of cellular recruitment to VCAM-1 contributes to atherosclerosis." (PMID 26332580, 2015). "To further validate this, we assessed inflammatory cytokine induced VCAM-1, the adhesion molecule involved in leukocyte-endothelial interaction in early atherosclerosis and is essential for disease progression." (PMID 26537113, 2015). "During the progression of atherosclerosis, adhesion molecules like VCAM-1 can promote monocyte adhesion to the intimal surface." (PMID 24621517, 2014). "NF-κB has been suggested to modulate endothelial inflammation and atherosclerosis through regulating inflammatory gene expression, such as VCAM-1." (PMID 24722330, 2014). "In this experimental model, the expression of ET-1 and inducible adhesion molecules such as ICAM-1, VCAM-1, and E-selectin in the arterial wall represent a key event in the development of atherosclerosis." (PMID 24719637, 2014). "In the present study, we found that loss of CCN3 was correlated with VCAM-1 and ICAM-1 expression in atherosclerosis, and the overexpression of CCN3 significantly inhibited the expression of these genes." (PMID 24722330, 2014). "VCAM-1 is thought to be a more specific marker for advanced atherosclerosis, since it is usually expressed in atherosclerotic plaques." (PMID 25045892, 2014). "One of the earliest events during the initiation of atherosclerosis is the high expression of adhesion molecules by vascular endothelial cells, including vascular cell adhesion molecule-1 (VCAM-1) and intercellular adhesion molecule-1 (ICAM-1)." (PMID 24722330, 2014). "As a key regulator of atherosclerosis, NF-κB regulates the expressions of various inflammatory factors, including VCAM-1, MCP-1, IL-6 and TNF-α, which in turn accelerate the progress of chronic inflammation." (PMID 24621517, 2014). "One of the earliest important events during the initiation of atherosclerosis is the expression of adhesion molecules by vascular endothelial cells, including VCAM-1 and ICAM-1." (PMID 24722330, 2014). "ICAM-1 and VCAM-1 were measured as markers of endothelial dysfunction; considered the earliest stage in the atherosclerosis process." (PMID 25115868, 2014). "It is assumed that ICAM-1, VCAM-1 and E-/P-selectin take part in the causal pathway leading to atherosclerosis as selectins mediate rolling of leukocytes along the endothelium and ICAM-1 and VCAM-1 lead to adhesion and transendothelial migration of leukocytes." (PMID 24276320, 2013). "VCAM-1 is a specific marker for advanced atherosclerosis, since it is often expressed in atherosclerotic plaques." (PMID 24129228, 2013). "Due to the small size of the murine model of atherosclerosis in our study, the expression of VCAM-1 was imaged in the aorta." (PMID 23554922, 2013). "Levels of soluble E-sel, ICAM-1 and VCAM-1 in blood plasma were significantly higher in patients with unstable angina, acute coronary syndrome and atherosclerosis." (PMID 23895132, 2013). "Previously, miR-126 was reported to participate in atherosclerosis regulation by targeting 3′ UTR of VCAM-1." (PMID 24237608, 2013). "We and others have also shown that under conditions of atherosclerosis progression, proteins such as VCAM-1 and ICAM-1 are up-regulated." (PMID 22761902, 2012). "As a transmembrane glycoprotein, VCAM-1 is upregulated and expressed at atherosclerosis-prone sites even before macroscopic disease is apparent, with persistent expression in more advanced atherosclerotic lesions." (PMID 22007259, 2012).
atherosclerosis (continued). "During the early stages of atherosclerosis progression endothelial cells express adhesion molecules (e.g. VCAM-1, ICAM-1, E-selectin) as well as chemokines (e.g. MCP-1, MCP-3, Fractalkine) upon activation of the nuclear factor-kappa B." (PMID 22383985, 2012). "In early part of atherosclerosis, nuclear factor-kappa B (NF-κB) induces the expression of cellular adhesion molecules such as vascular cell adhesion molecule-1 (VCAM-1), intracellular adhesion molecule-1 (ICAM-1) and E-selectin." (PMID 21496279, 2011). "Antibodies blocking either VCAM-1 or the β1 or β2 integrins greatly reduce monocyte adhesion, and genetic mutation of ICAM-1 or VCAM-1 reduces atherosclerosis in mice." (PMID 21264293, 2011). "The expression of the adhesion molecules intercellular adhesion molecule-1 (ICAM-1) and vascular cell adhesion molecule-1 (VCAM-1) in endothelial cells is the earliest known event in the initiation and progression of atherosclerosis." (PMID 21980456, 2011). "Initial leukocyte rolling is mediated by E- and P-selectin whereas firm adhesion to the vascular wall is mediated via integrin binding with intercellular adhesion molecule-1 (ICAM-1) and VCAM-1, with the latter more important in initiation of atherosclerosis." (PMID 19883911, 2010). "Different studies have provided evidence that VCAM-1 promotes the progression of atherosclerosis by accumulation, adhesion and trans-endothelial migration of leukocytes." (PMID 20920269, 2010). "VCAM-1 has, based on experiments with knockout mice, been recognized as the crucial adhesion molecule in the initiation of atherosclerosis." (PMID 19997643, 2009). "Thus CRP, ET-1,P-selectin, ICAM-1, and VCAM-1 levels are related to bothhyperglycemia and dyslipidemia and may reflect the presence of amultiple-risk factor clustering syndrome providing further supportfor the role of these markers in atherosclerosis." (PMID 17497038, 2007). "In this study, hypoglycemia did not result in changes in VEGFA, ICAM1, ICAM2 and VCAM1 as known mediators of endothelial dysfunction associated with atherosclerosis, stroke and myocardial infarction, as well as T2D microvascular complications." (PMID 41596469, 2026). "3,4-DHAP reduces the expression levels of TLR4, 5-lipoxygenase (5-LOX), and LTB4 in plaque macrophages while decreasing the expression of vascular cell adhesion molecule-1 (VCAM-1) in plaques, thereby slowing the progression of atherosclerosis and stabilizing plaques." (PMID 40298838, 2025). "Herein, seven novel anti-VCAM-1 monoclonal antibodies (mAbs) generated from phage display biopanning were tested using a series of in vitro models of cell recruitment to determine their potential utility for treating atherosclerosis." (PMID 41367412, 2025). "Th2 cells secrete IL-4, IL-5 and IL-13, among which IL-5 and IL-13 have been shown to have a protective effect on atherosclerosis, and IL-13 can reduce the infiltration of macrophages in plaques by decreasing the expression of vascular cell adhesion molecule-1 (VCAM-1)." (PMID 41268556, 2025). "Previous studies showed that RETN could accelerate the process of atherosclerosis by upregulating vascular endothelial adhesion factors such as VCAM-1 and ICAM-1." (PMID 40641746, 2025). "Inflammation and lipid abnormalities promote endothelial activation which is characterized by an increase in the adhesion molecules ICAM-1 and VCAM-1, which facilitates the recruitment of monocytes to the endothelium, initiating and accelerating the development of atherosclerosis." (PMID 40003621, 2025). "For example, this study has demonstrated that shear stress induces VCAM-1 via the NF-κB pathway in vascular endothelial cells, thereby upregulating the expression of CX3CR1—a process closely associated with the development of atherosclerosis." (PMID 41282026, 2025).
atherosclerosis (continued). "VCAM-1-antagonising peptides and antibodies have been widely utilised as targeting moieties for visualising inflammation and delivering anti-inflammatory agents in disease pathologies involving endothelial dysfunction, particularly atherosclerosis." (PMID 40095109, 2025). "ICAM-1 and VCAM-1 are intermittently expressed in endothelial cells and smooth muscle cells in normal arteries, with a high density in plaque-prone locations, and play a significant role in atherosclerosis and endothelial dysfunction." (PMID 40224490, 2025). "Recent studies in healthy populations have associated IL-32 with atherogenic lipoproteins and with monocyte endothelial adhesion mediated by intercellular adhesion molecule-1 (ICAM-1) and vascular cell adhesion molecule-1 (VCAM-1), a crucial step in atherosclerosis pathogenesis." (PMID 40299461, 2025). "Animal studies indicate that mild hyperbilirubinemia prevents atherosclerosis progression by improving lipid profiles and modulating the mRNA expression of vascular cell adhesion molecule 1 (VCAM-1), ICAM-1, inducible nitric oxide synthase (iNOS), and lectin-like LDL receptor 1 (LOX-1)." (PMID 40612433, 2025). "Higher VCAM-1 levels correlate with early atherosclerosis and plaque progression." (PMID 40217801, 2025). "However, as VCAM-1 assists in leukocyte adhesion to endothelium, it plays an important role in all stages of atherosclerosis." (PMID 39859506, 2025). "The pathophysiological role of VCAM-1 in atherosclerosis has been well documented." (PMID 41367412, 2025). "This study employs a series of in vitro assays modelling pathological monocyte recruitment during vascular inflammation to preliminarily evaluate the therapeutic potential of seven novel anti-VCAM-1 monoclonal antibodies (mAbs) as possible drug candidates for atherosclerosis." (PMID 41367412, 2025). "VCAM–1 has been identified as the most prevalent adhesion molecule in atherosclerosis." (PMID 40564977, 2025). "VCAM-1 plays a crucial role in atherosclerosis formation by promoting endothelial injury and the release of various cytokines that stimulate smooth muscle cell transformation and proliferation, leading to fibrous plaque formation and affecting plaque stability." (PMID 40529499, 2025). "CD40L and VCAM-1 are integral contributors to the development of atherosclerosis." (PMID 39787159, 2025). "Some studies have suggested that IL-9 may mediate the infiltration of inflammatory cells into atherosclerotic lesions by inducing the expression of VCAM-1 in aortic endothelial cells, thereby promoting atherosclerosis." (PMID 41268556, 2025). "Antibodies against vascular cell adhesion molecule (VCAM)-1 represent an attractive strategy for atherosclerosis and cardiovascular disease management due to their ability to selectively block leukocyte-endothelial interactions involved in inflammatory cell recruitment." (PMID 41367412, 2025). "Strikingly, 10 genes exhibited shared dysregulation in both aging and atherosclerosis, including Vcam1, Apoe, Gdf15, Timp1, Cxcl12, Hspd1, Serpine1, App, Eln, and Hif1a, suggesting their potentially critical roles in the atherosclerosis driven by aging in HGPS mice." (PMID 41209003, 2025). "VCAM-1 has already shown promising utility as a predictive biomarker for CVD, and the significant associations between VACM-1 and CVDs like hypertension, atherosclerosis, ischaemic heart disease, stroke, heart failure, arrhythmias, and atrial fibrillation have been discussed previously." (PMID 39830114, 2024). "They found that trans-lycopene from tomato juice may reduce CVD risk by lowering the concentration of inflammatory molecules associated with atherosclerosis, such as adhesion molecules ICAM-1, VCAM-1, and IL-8." (PMID 39599645, 2024).
atherosclerosis (continued). "VCAM-1 and ICAM-1 (Intercellular Adhesion Molecule 1) are upregulated in atherosclerosis lesions, but Cybulsky and collaborators demonstrated in mice models that VCAM-1 was involved in the initial stage of atherosclerosis while ICAM-1 was involved in lesion progression." (PMID 39273200, 2024). "In conclusion, MO is more potent than FO in preventing atherosclerosis, and the possible mechanism may be by downregulating p38MAPK/NF-κB signaling pathway, decreasing VCAM-1 and macrophage, and inhibiting proliferation and migration of SMC." (PMID 38410635, 2024). "Taken together, these findings suggest that the VCAM-1 expressed on plaque macrophages, and potentially on endothelial cells, rather than sVCAM-1 in the circulation, mediates α9β1-dependent neutrophil recruitment and NETosis in early atherosclerosis." (PMID 39036986, 2024). "In addition, VCAM1, NCF2, RAC2, MMP9, and ICAM1 were associated with fluid shear stress and atherosclerosis." (PMID 38640295, 2024). "VCAM-1 plays a pivotal role in the development of atherosclerosis." (PMID 38982470, 2024). "Sirt6 overexpression in atherosclerosis promotes macrophage autophagy and inhibits the expression of vascular cell adhesion molecule-1 (VCAM-1), ICAM-1, and platelet selectin (P-selectin), leading to reduced macrophage infiltration of macrophages and plaque stabilization." (PMID 39372420, 2024). "While other α9β1 ligands, including Fn-EDA, may also contribute to early atherosclerosis, the significant reduction in lesions observed in α9Mye-KOApoe−/− mice can be at least partially attributed to decreased VCAM-1-mediated neutrophil recruitment." (PMID 39036986, 2024). "Our in vivo findings demonstrated that FCBP effectively mitigates weight gain in a dose-dependent manner and reduces inflammatory markers (ICAM-1 and VCAM-1) in endothelial cells, suggesting its role in managing diet-induced obesity and preventing early atherosclerosis." (PMID 39534464, 2024). "The expression of VCAM-1 and ICAM-1, which are localized to the endothelium in atherosclerosis-susceptible arterial regions, precedes monocyte recruitment and forms important links between inflammation and atherosclerosis." (PMID 39113913, 2024). "Upon activation induced by H2O2, P90RSK inhibits transcriptional activation of ERK5 and adjusts the subsequent expression of KLF2-eNOS and VCAM-1, thus inhibiting endothelial cells (ECs) inflammation and modulating the function of the ECs, which is responsible for atherosclerosis." (PMID 38606153, 2024). "Therefore, VCAM-1 expression can be correlated with the extent of plaque formation, making VCAM-1 an ideal biomarker for atherosclerosis." (PMID 39769411, 2024). "Cell adhesion molecules (CAMs), such as ICAM-1 and VCAM-1, are produced by inflammatory cytokines; their levels indicate the inflammatory process occurring in the vascular endothelium; these are also considered early indicators of atherosclerosis." (PMID 39457107, 2024). "A main function of VCAM-1 is transendothelial migration of circulatory monocytes into the intima, whereby monocytes differentiate into macrophages and engulf LDL that has entered the intima, which can cause atherosclerosis development." (PMID 37504271, 2023). "Because vascular cell adhesion molecule 1 (VCAM-1) plays a major role in atherosclerosis, we investigated whether Shank3 modulates the tumor necrosis factor-α (TNF-α)–induced expression of VCAM-1." (PMID 37947623, 2023). "Moreover, A151 can significantly reduce the levels of two key inflammatory factors, monocyte chemotactic protein 1 (MCP-1) and vascular cell adhesion molecule 1 (VCAM-1), in the inflammatory process of atherosclerosis." (PMID 36825156, 2023). "Some other inflammatory factors such as monocyte chemoattractant protein-1 (MCP-1), intercellular adhesion molecule-1 (ICAM-1), and vascular cell adhesion molecule-1 (VCAM-1) play crucial role in recruitment of inflammatory monocytes into vascular wall and initiate atherosclerosis." (PMID 36627567, 2023).
atherosclerosis (continued). "However, experiments using VCAM-1 and ICAM-1 knockout mice have reported that VCAM-1 plays a major function compared to ICAM-1 in the early stage of atherosclerosis." (PMID 37998401, 2023). "Generally, VCAM-1 is highly expressed on the injured endothelium, and it is related to the firm adhesion of leukocytes to the endothelium and plays an important role in the development of atherosclerosis by recruiting leukocytes into the sub-endothelial space." (PMID 36482036, 2023). "By chemically modifying a nanobody and covalently fusing it to azidified silicon wafers, BiacoreTM C1 sensor chips, and boron-doped microcrystalline diamond films, Duy Tien Ta (2016) created a biosensor platform that can detect the VCAM-1 atherosclerosis biomarker." (PMID 37375810, 2023). "The enhanced induction of VCAM1 expression in endothelial cells by circulating factors may play a role in the development of atherosclerosis in diabetes." (PMID 36820318, 2023). "Inflammatory modulators/biomarkers, such as IL-1α, IL-1β, IL-6, IL-12, IL-15, IL-18, and tumor necrosis factor α, or alternative anti-inflammatory cytokine IL-10, and adhesion molecules (ICAM-1, VCAM-1), involved in atherosclerosis progression have been shown to predict cardiovascular diseases." (PMID 37374202, 2023). "Moreover, buspirone directly induced the normalization of hypertension through reducing the expressions for AT1R and VCAM1 related to atherosclerosis." (PMID 37168052, 2023). "ICAM-1 and VCAM-1 overexpression promotes ED, which is an early stage of atherosclerosis." (PMID 37374202, 2023). "As high plasma cholesterol levels are related to the development of CVD, we determined how different kefir preparations impacted circulating levels of VCAM-1 and CRP, which are important factors in the development of atherosclerosis and common biomarkers of CVD risk." (PMID 36504827, 2022). "Expression of the adhesion molecule VCAM-1 occurs early during atherogenesis and may, therefore, serve as a useful imaging biomarker of inflammation in atherosclerosis." (PMID 35631669, 2022). "It is observed that, in comparison with the control group, the endothelium of apoE-/- mice with S1 or S3 treatment showed less TUNEL positive area and decreased ICAM-1 and VCAM-1 protein level, suggesting S1 and S3 inhibited endothelium injury during atherosclerosis development." (PMID 35335352, 2022). "The dysfunction in psoriasis includes systemic inflammation involving cytokines, such as IL-17, TNF-α and IFN-γ, as well as inflammatory transcripts such as CXCL10, IL-1β and VCAM-1.Psoriasis increases vascular stiffness and atherosclerosis tthrough the IL-17 pathway." (PMID 36211578, 2022). "In addition to inhibiting aortic VCAM-1 expression, NLR, an inflammatory marker associated with atherosclerosis, was also reduced by capsanthin treatment." (PMID 35892680, 2022). "VCAM-1 and ICAM-1 are involved in the adhesion of cells, while VCAM-1 may play a role in the development of rheumatoid arthritis and atherosclerosis." (PMID 35893855, 2022). "Studies have reported that VCAM-1 expression increases in the early stages of atherosclerosis." (PMID 35631669, 2022). "Therefore, anti-VCAM-1 monoclonal antibodies (mAbs) have been investigated as a therapeutic agent for atherosclerosis." (PMID 35135581, 2022). "Importantly, the proteins Gal-3 and VCAM1, which are key participants of atherosclerosis pathogenesis, revealed lower expression after a low-iron diet." (PMID 36555552, 2022). "To determine whether VCAM1+ SMCs were involved in atherosclerosis, we examined the presence of VCAM1+ SMCs in ApoE–/– mice fed with Western diets." (PMID 36278486, 2022). "Our findings also suggest that VCAM1+ SMCs could be induced by other vascular injuries such as ligation, in addition to atherosclerosis." (PMID 36278486, 2022).